C3 (complement C3)
Diseases named in the same sentence as C3 in open-access papers (continued):
Sharing a sentence is not in itself a finding about the gene and the disease.
preeclampsia (22 papers, 2014 to 2025). Preeclampsia is a hypertensive disorder of pregnancy that is characterized by new-onset hypertension with proteinuria presenting after 20 weeks of gestation, and depending on mild or severe forms may initially present with severe headache, visual disturbances, and hyperreflexia. "Excessive activation of the complement system is likely involved in placental dysfunction and pregnancy complications such as preeclampsia, as preeclamptic mouse models are associated with deposition of complement component 3 (C3) in placentas." (PMID 40249643, 2025). "The C3 complement also plays an important role in cellular senescence in age-related PBs and has been associated with severe preeclampsia." (PMID 37450933, 2024). "C3 is implicated in the development of preeclampsia through bioinformatics-based identification." (PMID 35069847, 2022). "Elevated C3 levels have been associated with preeclampsia and the development of macrosomia." (PMID 33859618, 2021). "Elevated C3 expression in neurons in the brain of patients with severe preeclampsia is consistent with the cellular expression of senescent phenotype neurons in the brains and cerebrospinal fluid of patients with Alzheimer's disease." (PMID 37450933, 2024). "Mutations in the FOXD1 gene are also related to RIF, intrauterine growth restriction, and preeclampsia through the regulation of angiogenesis and vasoconstriction-related genes, including complement component 3 (C3) and placental growth factor (PlGF)." (PMID 39498089, 2024). "The serum concentration of C3 is elevated in women with preeclampsia compared with normal pregnant women." (PMID 35069847, 2022). "Compared to controls, preeclampsia prone rats showed decreased circulating C3 and increased C3a, indicating that complement activation has occurred." (PMID 32010144, 2019). "Levels of C3 were also measured in the circulation of women with preeclampsia, but these findings were comparable with control groups." (PMID 32010144, 2019). "In human, it has been reported a potential linkage of severe preeclampsia to the most central complement gene, C3." (PMID 31374089, 2019). "The levels of C4d, C3a, C5a, C5b-9 observed for preeclampsia women were increased when compared to healthy pregnant ones, and accompanied with lowered C3 level." (PMID 24030732, 2014). "In our cohort, the high rates of probable disease activity in pregnancy (as evidenced by the first trimester findings of low C3 and proteinuria), could have also contributed to the high rate of preeclampsia." (PMID 39139800, 2024). "Furthermore, the investigation identified a number of genetic variants in the genes of ADAMTS13, C3, CFH, CFB, thrombomodulin, MBL2, and MASP2 that were significantly linked with the occurrence of preeclampsia, according to the results of analyses A and B." (PMID 38673014, 2024). "Besides that, there is a correlation between C3 activation and enhanced terminal complex formation in women with preeclampsia, compared to controls." (PMID 32010144, 2019). "Fetal cord blood factor B levels do not vary during healthy pregnancy and preeclampsia, and other complement components (C1q, C3, C4, and C3d) are much lower than those in healthy maternal circulation." (PMID 40904461, 2025).
retinal degeneration (22 papers, 2012 to 2025). Degeneration of the retina. "In this study, we show that the expression of C3 and C3a receptor (C3ar1) is positively associated with the inflammatory response and retinal degeneration." (PMID 36110094, 2022). "Both C3 activation and depletion have been associated with retinal degeneration, indicating that careful control of C3 expression and its cleavage fragments needs to be considered for AMD therapies." (PMID 32815311, 2020). "C3 deficiency partially rescued photoreceptor cell apoptosis and preserved visual function by promoting the antioxidative signaling pathway and effectively attenuated a DNA alkylating agent-induced retinal degeneration." (PMID 35676725, 2022). "Taken together, our results indicate that MASP-3 plays a pivotal role in C3 activation in the retina most likely via activation of the AP leading to the development of retinal degeneration in the NaIO3-induced murine dry AMD model." (PMID 40226626, 2025). "Although C3ar1 is involved in retinal development and neuropathy, the role of the C3-C3ar1 axis in retinal degeneration is less understood." (PMID 36110094, 2022). "Since we found an increase in the production of C3 in the MMS-treated mouse retina, we aimed to elucidate the function of C3 using the MMS-induced retinal degeneration model." (PMID 35676725, 2022). "In summary, our study found that C3 KO promotes photoreceptor cell survival and activates the Nrf2 signaling pathway in the context of alkylation-induced retinal degeneration." (PMID 35676725, 2022). "Our RNA-seq analysis results revealed significant activation of the C3/C3aR/STAT cascade in the NaIO3-induced retinal degeneration model." (PMID 36110094, 2022). "Our findings suggest that the expression of C3 increases in the aging rat retina, due to the local synthesis of C3 by monocytes/microglia, and further implicate complement in the progression of retinal degeneration." (PMID 24705166, 2014). "Mice immunized with the oxidative damage by-product CEP develop retinal degeneration and show increased deposition of complement C3 in the outer retina." (PMID 24705166, 2014). "Using reverse transcriptase PCR, upregulated retinal C1qβ and C3 expression has been shown in light-induced models of retinal degeneration." (PMID 26237601, 2014). "Q-PCR analyses showed J cybrids had decreased expressions for CFH, C3, and EFEMP1 genes, high risk genes for AMD, and higher expression for MYO7A, a gene associated with retinal degeneration in Usher type IB syndrome." (PMID 23365660, 2013). "This is consistent with the investigations by Hollyfield and colleagues, in which mice immunized with the oxidative damage byproduct CEP develop AMD-like retinal degeneration and show increased deposition of complement C3 in the outer retina." (PMID 23181358, 2012). "Likewise, the genetic deletion of complement C3 in microglia reduced neuroinflammatory damage in retinal degeneration models." (PMID 41403938, 2025). "Furthermore, in a light‐induced model of progressive retinal degeneration in rats, C3 was detected in retinal macrophages and the sub‐retinal space, particularly at the margins of the emerging lesion, suggesting a similar role in atrophic AMD." (PMID 36203396, 2023). "Moreover, C3 KO promotes photoreceptor cell survival and activates the Nrf2 signaling pathway in the context of alkylation-induced retinal degeneration." (PMID 35676725, 2022). "All these changes potentially suggest that C3 inhibition may be protective against retinal degeneration." (PMID 28928904, 2017). "However, it is clear that both too little and too much C3 activation is associated with retinal degeneration, suggesting that balanced C3 activation is required for normal eye health." (PMID 36203396, 2023). "However, whether C3 activation is involved in DNA-alkylating agent-induced retinal degeneration is unclear." (PMID 35676725, 2022).
retinal degeneration (continued). "However, the contribution of each complement pathway to C3 activation is still largely unknown, impeding the development of effective anti-complement drugs for retinal degenerations." (PMID 30126455, 2018). "Overall, TDIPs effectively suppressed the TLR‐mediated upregulation of C3, thereby protecting the RPE and reducing photoreceptor cell death under NaIO3‐induced retinal degeneration conditions." (PMID 39482884, 2025). "The real-time RT-PCR was conducted to examine the expression of complement genes (C1q, C2, C3, C4, CFI and CFD) in the guinea pig model of long-term form deprivation-induced myopic retinal degeneration." (PMID 37448698, 2023). "C3 mRNA was expressed in the aging retina by cells immunoreactive for the monocyte/microglia marker IBA1, consistent with our previous findings in a light-induced model of retinal degeneration." (PMID 24705166, 2014). "This may indicate that the effector functions enabled by the classical complement pathway may be independent of hydrolysis of C3, which is predominantly amplified by the alternative complement pathway in photo-oxidative damage models of retinal degeneration." (PMID 30126455, 2018).
bullous pemphigoid (21 papers, 2009 to 2025). Bullous pemphigoid (BP) is the most common form of autoimmune bullous dermatosis. "C3 deposits were predominantly seen in bullous pemphigoid (12 cases with 2+), with a significant association observed between C3 positivity and HPE diagnosis (p = 0.002)." (PMID 41362514, 2025). "Immunofluorescence studies showed strong IgG and C3 positivity at the dermo-epidermal junction, which was diagnostic of bullous pemphigoid." (PMID 19448374, 2009). "Furthermore, passive transfer of autoantibodies from bullous pemphigoid patients was shown to induce blister formation in neonatal C3-deficient collagen XVII-humanized mice." (PMID 30524436, 2018). "was in fact considered to have bullous pemphigoid with cutaneous blisters, IgM and complement C3 depositions along the BMZ by direct IF microscopy, and circulating anti‐BMZ autoantibodies." (PMID 40765425, 2025). "The gold standard for diagnosing bullous pemphigoid (BP) is the detection of linear deposition of IgG and/or C3 at the dermoepidermal junction using direct immunofluorescence (DIF)." (PMID 35732698, 2022). "Mucosal biopsy for direct immunofluorescence (DIF) revealed “linear IgG and C3 and IgA at dermal-epidermal junction, and on roof of salt split skin” consistent with bullous pemphigoid, mucous membrane pemphigoid (MMP), or linear IgA bullous disease." (PMID 35740129, 2022). "Direct immunofluorescence was characteristic of bullous pemphigoid (BP), with linear IgG and C3 at the basement membrane." (PMID 36479274, 2022). "Similar to classical bullous pemphigoid, a continuous linear deposits of complement component 3 (C3) and immunoglobulin G (IgG) along the dermoepidermal junction and blister roof." (PMID 33924249, 2021). "We did a pragmatic, multicentre, parallel-group randomised controlled trial of adults with bullous pemphigoid (three or more blisters at two or more sites and linear basement membrane IgG or C3)." (PMID 28279484, 2017). "Bullous pemphigoid (BP) is the most common subtype of autoimmune blistering diseases that primarily affects the elderly and is classically defined by the presence of IgG and/or complement C3 against the BP180 and BP230 hemidesmosome proteins." (PMID 36405625, 2022). "In bullous pemphigoid, on the other hand, histologically a sub-epidermal blister containing numerous eosinophils and neutrophils is observed and direct immunofluorescence shows linear deposits of C3 and IgG (BP180) at the level of the basement membrane." (PMID 34209865, 2021). "We therefore hypothesized that loss of CD55, a typical complement regulator acting via suppression of C3 and C5 activity, contributes to bullous pemphigoid development." (PMID 30473747, 2018). "Bullous pemphigoid and cicatricial pemphigoid typically localize both IgG and C3 at the basement membrane (IgA and IgM may be seen) but epidermolysis bullosa acquisita and bullous systemic lupus erythematosus usually have multiple classes of immunoreactants." (PMID 23110919, 2012). "Paraneoplastic pemphigoid is suggested to be a distinct entity from the group of bullous pemphigoid in view of the linear C3 deposits along the basement membrane of the perilesional skin and the “ladder” configuration of autoantibodies demonstrated by western blot analysis." (PMID 23320017, 2012). "However, immunofluorescence studies may be required to exclude clinically similar conditions (e.g., bullous pemphigoid, epidermolysis bullosa acquisita, and porphyrias) that typically show deposition of C3 and immunoglobulin G along the basement membrane zone." (PMID 23119191, 2012). "Bullous pemphigoid exhibited a linear BMZ pattern with IgG and C3 deposition, showing moderate intensity in 10 and weak intensity in 3 cases." (PMID 41362514, 2025). "Anti-BP180 IgE was also detected via direct immunofluorescence (DIF) in 41% of patients with bullous pemphigoid, and in 5% of cases the diagnosis was made just by the detection of IgE with DIF, with negativity for IgG and C3." (PMID 36359364, 2022).
bullous pemphigoid (continued). "These two fragments competitively inhibit the binding of bullous pemphigoid autoantibodies to the main BP180 NC16A epitope, blocking subsequent activation of complement components C1q and C3." (PMID 30473747, 2018). "A second biopsy for direct immunofluorescence DIF showed linear deposits of IgG and C3 at the epidermal BMZ, confirming the diagnosis of bullous pemphigoid." (PMID 28228112, 2017). "Bullous pemphigoid, although rare in children, was also evaluated; the absence of linear IgG and C3 deposition on DIF and the patient’s age made this diagnosis less likely." (PMID 40995939, 2025). "The most frequent DIF findings are the presence of linear deposits of C3 and IgG in the BMZ, whereas IFI, with the salt-split skin technique, allows the differentiation from EBA, since in bullous pemphigoid, fluorescence occurs on the epidermal or epidermal and dermal sides of the cleavage." (PMID 35701269, 2022).
complement deficiency (21 papers, 2012 to 2025). A genetic deficiency of any of the component of the complement system (including the classical, alternative, and terminal pathway components), that can either be acquired or inherited. "Low C3 represents immune consumption and deposition in the kidneys; however, a primary complement deficiency seen in a subset of pSLE patients can be a confounding factor, particularly with low C4 levels." (PMID 36688943, 2023). "Acquired complement deficiency and low levels of C3, C4 and CH50 were previously reported to increase the risk of infection caused by S. aureus infection." (PMID 35572551, 2022). "Complement deficiency is commonly detected in the laboratory by quantifying the main soluble fragments C3 and C4 formed during activation." (PMID 33193314, 2020). "Initial discussions primarily relied on theoretical considerations of primary complement deficiencies, whereas C3 deficiency often leads to a broader range of susceptibilities to infections, which is mostly attributed to the opsonic activity of C3b." (PMID 32973774, 2020). "Pediatric patients with the diagnosis of SLE can develop very low C3 levels that associate with risk of serious bacterial infection comparable to that of patients with primary complement deficiency." (PMID 32972440, 2020). "Although complement deficiency is rare in humans, genetic polymorphisms in complement proteins such as factor I, factor B, C3 and factor H are known to affect their availability, activity, and susceptibility to chronic disease conditions." (PMID 23326231, 2013). "The kidney injury could be attenuated by inducing complement deficiencies (C3, factor D or factor B deficiency) and could be increased in mice deficient in complement regulators (factor H deficiency)." (PMID 32447506, 2020). "Thus, C3’s involvement in immune responses and tissue repair highlights its potential as a target for enhancing vaccine efficacy, especially in individuals with complement deficiencies who might benefit from C3 supplementation to improve both immune functions and pathogen clearance." (PMID 40592462, 2025). "Both rare monogenic traits, such as terminal complement deficiencies of C5-C9, CFD, CFB, CFI, and C3, and common polymorphisms in the CFH/CFHR3 region have been found in association with IMD." (PMID 32067109, 2020). "The lung cross-species signature includes multiple carcinoma-associated genes (TNR, SCD) and, to a lesser extent, genes involved in complement deficiency (CFD, C3) and NAD+ metabolism (NNMT), all of which may be considered aging-associated processes." (PMID 40249926, 2025). "It has been suggested that C3b opsonization contributes to host defense as patients with C3 complement deficiency suffer from Hib infections rather than individuals with membrane attack complex (MAC, C5b-C9) deficiencies." (PMID 36578495, 2022). "We could suspect the possibility of complement deficiency with the result of undetectable CH50 activity, despite normal activities of C3 and C4 components." (PMID 33787610, 2021). "C3 elevation could also occur as compensatory response to complement deficiency in the airway yet may not be sufficient for control of NTM infection in the airway environment." (PMID 36651756, 2023).